CTSS (cathepsin S)
Diseases named in the same sentence as CTSS in open-access papers (continued):
Sharing a sentence is not in itself a finding about the gene and the disease.
infection (73 papers, 2009 to 2026). The state of being infected such as from the introduction of a foreign agent such as serum, vaccine, antigenic substance or organism. "Other host proteins that were not recurring across the 15 interactomes but common in other interactomes such as HYOU1, PDIA3, HSPA9, CTSS, etc., have been already also found deregulated upon pathogenic infection." (PMID 30815000, 2019). "Previously we hypothesized that the noticeable Mtb-induced decrease in cathepsin S expression during infection might be linked to poor antigen processing and presentation, compromising the adaptive immunity response to infection." (PMID 33841429, 2021). "We then hypothesized that Mtb modulation of miR-106b-5p for CtsS silencing might be linked to poor antigen processing and presentation compromising adaptive immunity response to infection." (PMID 29326705, 2017). "So, in both infection groups (viable and HK), up-regulation of CTSS might be linked to degradation of phagocytized particles and antigen presentation." (PMID 27014637, 2016). "Among these ECM-related proteases, CTSS—a lysosomal cysteine proteinase—displayed the most prominent upregulation, correlating with dose and duration of infection." (PMID 41258714, 2026). "Mechanistically, we observed subcellular redistribution of CTSS from lysosomes into the cytoplasm during the late stages of infection, consistent with LMP." (PMID 41258714, 2026). "Because CTSS activity increased in supernatants after infection and CTSS targets ECM and junctional components, we tested effects on epithelial barrier function." (PMID 41258714, 2026). "Dipeptidyl peptidase 1 (cathepsin C) and cathepsin S were increased 1.53 and 1.71 fold respectively at 24 hours post infection." (PMID 40665229, 2025). "Intriguingly, the gene coding cathepsin S was the only gene significantly upregulated among the studied genes after infection with reovirus (p (Spearman) = 4.55 × 10−5) in all glioblastoma cell lines." (PMID 39772250, 2024). "In an in vitro study with human macrophages, infection with Mycobacterium bovis bacillus Calmette–Guérin (BCG) induced the inhibition of CTSS with IL-10 and consequently reduced MHC class II antigen presentation." (PMID 38668343, 2024). "We also observed significant reduction of infection in cultures expressing CTSS in both A549-SunTag ACE2 and A549ΔSTAT1-SunTag ACE2 cultures, confirming its activity as a novel SARS-CoV-2 restriction factor." (PMID 35421191, 2022). "Similar to C4A, CTSS expression experiences >1.5 fold change over the course of infection, but this gene is also significantly increased at each chronic time point." (PMID 33816350, 2021). "Infection with MAH and M. tuberculosis inhibits the maturation of cathepsin L, while infection with M. bovis BCG inhibits expression of cathepsin S." (PMID 31117286, 2019). "In present study, increased CTSS expression at 4 h post infection was observed and miR-3619-5p was down-regulated already at 15 min." (PMID 27014637, 2016). "Furthermore, CTSS enzymatic activity in A549 cell lysates increased in a dose-dependent manner after infection, and the activity of CTSS in the cell supernatant was also slightly increased." (PMID 41258714, 2026). "In addition, we found that high-dose infection further increased the accumulation of activated-CTSS." (PMID 41258714, 2026). "Since the outer capsid processing of various reoviruses in macrophage-like cells has been associated with endopeptidase cathepsin-S, the regulation of endopeptidase activity in ARV-infected HD11 cells suggests a potential cellular response to infection to prevent ARV entry and disassembly." (PMID 41305511, 2025). "Therefore, infection with rBCG::CatS producing cathepsin S was expected to restore cathepsin S function and enhance MCH class II antigen presentation." (PMID 35632582, 2022). "B. abortus up-regulated cathepsin S mRNA at 72 h post-infection." (PMID 32629846, 2020).
infection (continued). "Altogether, miR-106b-5p modulates CtsS expression in human Mø during infection with Mtb." (PMID 29326705, 2017). "Therefore, regulation of CTSS at 4 h post infection is consistent with the co-localization of LAMP1 signals as a late marker of phagolysosomal processing." (PMID 27014637, 2016). "Moreover, the black rockfish that were treated with CTSS knockdown showed clearly higher bacteria amounts versus the control after the infection, while the fish that underwent the CTSK knockdown exhibited significantly lower bacterial amounts than the control group." (PMID 40422803, 2025). "Thus, the IRF-1/CTSS pathway could be modulated by cytokines, microRNAs, and pharmaceuticals, which mediates inflammatory pathology in radiation injury, infections, genetic disorders, and pharmacogenetic diseases." (PMID 40692794, 2025). "It is known that cathepsin S played an important role in the regulation of autophagy and apoptosis in human glioblastoma cells; on the other hand, this may support acid-independent infection by some reoviruses." (PMID 39772250, 2024). "Compared with the mock group, CTSS activity was significantly elevated in the placebo group following infection, whereas LY3000328 treatment significantly suppressed CTSS activity relative to the placebo group." (PMID 41258714, 2026). "Cathepsin S (CTSS) has recently garnered attention for its role in inflammation and infection (11, –, 13)." (PMID 41258714, 2026). "Some genes were significantly different at 24 hpi with EBOVΔVP30 infection (ATG, CTSS, IFNAR1); however, the differences in expression were small." (PMID 41472248, 2025). "In contrast to infection with lower pathogen vaccine strain BCG, we detected a higher abundance of CTSS in MAP-infected dairy cows." (PMID 38668343, 2024). "CTSS knockdown significantly increased TEER and restored E-cadherin expression, indicating improved tight junction integrity and epithelial cohesion during infection." (PMID 41258714, 2026). "Finally, the release of cathepsin S, which is able to promote M2/TAM macrophage polarization, was found to be strongly increased by HHV-6A-infection." (PMID 37896899, 2023). "According to those facts, animals with elevated cathepsin S in serum should be resistant against infection with Leishmania, which is not the case in our work." (PMID 36984805, 2023). "A differential regulation of CtsS was already observed in previous published results when comparing the infection of the non-virulent species M. smegmatis with macrophage infection with Mtb." (PMID 29326705, 2017). "Also CTSS has the potential to cleave and inactivate SLPI which further increases NE levels and facilitates bacterial colonization and infection." (PMID 26185365, 2015). "Moreover, while cathepsin D/E activity was not affected by infection, the activity of lysosomal cathepsin S was significantly reduced in HSV-1–infected LUHMES cells, suggesting a defect in lysosomal proteolytic function." (PMID 41596294, 2026). "In contrast, the infection with a BCG strain that secreted active human CTSS led to an increased MHC class II mycobacterial antigen presentation on the surface of macrophages, which shows that BCG does not directly inhibit MHC class II presentation, but its expression is dependent on CTSS." (PMID 38668343, 2024). "Interestingly, the function of miR-106b-5p on CtsS activity in the context of infection was independent of autophagy." (PMID 29326705, 2017). "Similarly, siRNA-mediated knockdown of CTSS in A549 cells led to decreased production of proinflammatory cytokines, reduced cleavage of the apoptotic marker PARP1, and preserved E-cadherin expression, thereby maintaining tight junctions and epithelial barrier function during infection." (PMID 41258714, 2026).
cardiovascular disease (35 papers, 2010 to 2025). "CTSS encodes cathepsin S (CTSS), which is mainly involved in the pathogenesis of a variety of cardiovascular diseases by mediating the degradation of extracellular matrix (ECM) proteins." (PMID 36602538, 2023). "Specifically, cathepsin S has been implicated in elastin degradation in cardiovascular disease, and high levels of cathepsin S have been described in the atheroma plaque." (PMID 33322093, 2020). "A variation in Cathepsin S (CTSS), a cysteine protease has been shown to be associated human metabolic risk factors for cardiovascular diseases." (PMID 20122255, 2010). "As such, RNA editing of specific nucleotides across a hotspot of editing, the Alu region of CTSS, was strongly correlated with CTSS expression and cardiovascular disease clinical outcomes in the biomaterial of patients with different stages of ASCVD." (PMID 36239832, 2023). "In general terms, dysregulation of cathepsins (CTSs) expression and/or activity, impairing cellular homeostasis, leads to a variety of human diseases, including, cardiovascular diseases, neurodegenerative disorders, and kidney dysfunctions." (PMID 36613802, 2022). "CTSS is an important player in the pathogenesis of several cardiovascular diseases, such as atherosclerosis, post-myocardial infarction remodeling and abdominal aortic aneurysm (AAA)." (PMID 32398133, 2020). "Other researchers have also inquired about various cathepsin S inhibitors as treatment for cardiovascular disorders." (PMID 29379789, 2017). "Studies aimed to explore the potential of CTS inhibitors for the treatment of cardiovascular diseases are ongoing, and targeting CTSs–based therapy might provide new avenues for the treatment of MPSs as well." (PMID 32326609, 2020). "Although cathepsin inhibitors, including cathepsin S inhibitors, have been extensively studied for their anti-inflammatory and antitumor properties, very few researchers have investigated the medicinal plants used in the treatment of cardiovascular disease for cathepsin S inhibition." (PMID 40647052, 2025). "A variety of evidence demonstrate that abnormal expression and/or activity of both lysosomal and extra-lysosomal CTSs correlate with MPS major clinical manifestations such as neuropathology, bone and joint defects, and cardiovascular disorders." (PMID 32326609, 2020). "Even though obese patients and patients who had T2D combined with cardiovascular disease showed increased levels of plasma CTSS, NALFD patients did not have different levels of plasma CTSS compared to healthy controls." (PMID 36289617, 2022).
neurodegenerative disease (13 papers, 2010 to 2025). A disorder of the central nervous system characterized by gradual and progressive loss of neural tissue and neurologic function. "The involvement of microglial CTSB, CTSD, and CTSS in neurodegenerative diseases supports the view that microglia-driven neuroinflammation contributes to the progression of neurodegeneration in MPS I and IIIB." (PMID 32326609, 2020). "Several cathepsins are found in CNS cells, and cathepsin S and B in particular have suggested roles in neurodegenerative diseases." (PMID 31569504, 2019). "Moreover, CTSS inhibitors have shown neuroprotective and anti-inflammatory effects in preclinical studies for the treatment of neurodegenerative diseases, although CTSS essential role in CNS homeostasis might limit its therapeutic applications." (PMID 32326609, 2020).
kidney disease (11 papers, 2015 to 2025). "Cathepsin S is a macrophage-derived proteolytic enzyme and has been implicated in the destruction of glomerular structures in many renal diseases." (PMID 38731158, 2024). "New evidence shows that lysosome protease cathepsin (CTSS) plays an essential role in the pathogenesis and progress of kidney diseases." (PMID 34819020, 2021). "More specifically, we will analyze inquiries into cathepsin S mechanism of action, its role in various processes of inflammation, calcification, and renal disease, and identify cathepsin S inhibitors that have been gaged as potential and promising treatment targets." (PMID 29379789, 2017).
bacterial infection (8 papers, 2018 to 2025). "In the process of the inflammatory response, CTSS is highly expressed in many immune cells and is considered to play a key role in the immune response after bacterial infection." (PMID 35806111, 2022). "This is in accordance with the increased cathepsin S activity during bacterial infection." (PMID 34867965, 2021).
metabolic disease (6 papers, 2020 to 2025). A congenital disorder (due to inherited enzyme abnormality) or acquired (due to failure of a metabolically important organ) disorder resulting from an abnormal metabolic process. "Patients with progressive metabolic disease (Deauville score 5, n=6) had increased CTSS levels by 25% after therapy." (PMID 39712508, 2024).
neurological diseases (5 papers, 2011 to 2025). "In conclusion, based upon the results of our comprehensive analysis of HHV-6A infected HA1800 cells, we revealed several genes correlated with neurologic disorders, especially CTSS, PTX3, CHI3L1, Mx1, CXCL16, BIRC3, and BST2 genes." (PMID 27344170, 2016). "Another study representing the first transcriptome sequencing study proposed the association of seven genes (CTSS, SERPINA1, NPTX1, PTX3, CHI3L1, SERPINA3, and MX1) as “the missing link” to explain the correlation between HHV-6A infection and neurological diseases." (PMID 35683449, 2022).
digestive system tumors (3 papers, 2008 to 2024). "This analysis encompassed a total of nine cathepsins include cathepsin B, cathepsin E, cathepsin F, cathepsin G, cathepsin H, cathepsin L2, cathepsin O, cathepsin S, and cathepsin Z, and six digestive system tumors (HCC, PCa, BTC, CRC, GC, and EC)." (PMID 38590662, 2024).
inflammation (3 papers, 2015 to 2026). Aberrant reaction of the microcirculation characterized by movement of fluid and leukocytes from the blood into extravascular tissues. "Activity inhibition of CTSS in mice did not alter pulmonary viral titers but significantly alleviated lung inflammation, reduced disease severity, and improved survival." (PMID 41258714, 2026).
peripheral neuropathy (3 papers, 2021 to 2025). A disorder affecting the peripheral nervous system. "Furthermore, the serum level of CTSS may serve as a biomarker for the risk of oxaliplatin-induced peripheral neuropathies." (PMID 33754020, 2021). "Our previous study demonstrated that targeting CTSS suppressed proinflammatory cytokine secretion and promoted anti-inflammatory cytokine secretion, protecting neurons from oxaliplatin-induced peripheral neuropathy, indicating that the inhibition of CTSS reduced tissue inflammation." (PMID 38725007, 2024). "We further investigated whether serum CTSS level could serve as a predictive biomarker of oxaliplatin-induced peripheral neuropathy." (PMID 33754020, 2021).
lung (2 papers, 2011 to 2024). "Apoe-/- mice treated with a selective cathepsin S inhibitor did not develop lung granulomas and only individual epithelioid cells were observed." (PMID 21251246, 2011).
respiratory diseases (2 papers, 2012 to 2025). "Considering the involvement of cathepsin S in respiratory diseases and in inflammation, it remains to be investigated whether the N protein of SARS-CoV-2 affects the expression of cathepsin S in lung airway epithelium, and if so, which downstream consequences are effectuated." (PMID 40076291, 2025).
CTSS also shares sentences with these, for which no sentence is quoted: immune diseases (6 papers); Gaucher disease (4); adenocarcinoma (3); brain cancer (3); dental caries (3); epilepsy (3); esophageal cancer (3); heart disease (3); Hepatitis (3); IgA nephropathy (3); mucolipidosis II (3); Parkinson disease (3); schistosomiasis (3); acute myeloid leukemia (2); age-related macular degeneration (2); airway hyperresponsiveness (2); amyotrophic lateral sclerosis (2); basal cell carcinoma (2); bipolar affective disorder (2); brain disease (2); calcific aortic valve disease (2); carotid atherosclerotic disease (2); cerebral aneurysm (2); depression (2); diabetic retinopathy (2); encephalomyelitis (2); endometrial cancer (2); Fasciola infection (2); hematologic malignancies (2); idiopathic pulmonary fibrosis (2).
A further 127 diseases each share a sentence with CTSS in 2 papers or fewer.